FBP1 (fructose-bisphosphatase 1)
Diseases named in the same sentence as FBP1 in open-access papers (continued):
Sharing a sentence is not in itself a finding about the gene and the disease.
tumor (continued). "In Huh-7 and SMMC-7721 cells, HSF2 was shown to interact with euchromatic histone lysine methyl transferase 2 (EHMT2) in order to epigenetically silence the gene encoding fructose-bisphosphatase 1 (FBP1), which is a tumor suppressor and negative regulator of aerobic glycolysis." (PMID 32408596, 2020). "Tumor-induced FBP1 and mitochondrial fragmentation account for impaired NK cell anti-tumor functions by compromising glycolysis and mitochondrial respiration, respectively, and targeting them can enhance NK cell-based tumor immunosurveillance." (PMID 32983138, 2020). "Our study also showed that FBP1 expression was correlated with tumor size, tumor grade, and SUVmax." (PMID 30723389, 2019). "However, FBP1 expression levels differed in tumor grade (P=0.023), SUVmax (P=0.020), and tumor size (P=0.003)." (PMID 30723389, 2019). "Moreover, panobinostat can affect cancer metabolism and tumor growth by restoring the expression of a key gluconeogenesis enzyme, fructose-1,6-bisphosphatase (FBP1), which is silenced by histone deacetylation in many cancers." (PMID 31056726, 2019). "Furthermore, dual‐specificity phosphatase 10 (DUSP10, MKP5) and downregulated FBP1 expression in drug‐resistant NSCLC tumor cell lines were observed among the three datasets." (PMID 31025554, 2019). "This unique dual function of the FBP1 protein explains its ubiquitous loss in ccRCC, distinguishing it from other tumor suppressors that are not consistently mutated in all tumors." (PMID 31484429, 2019). "Mounting evidence suggests that FBP1 acts as a tumor suppressor in multiple cancer types." (PMID 29991493, 2018). "The co-knockdown of FBP1 and c-Myc blocked FBP1 knockdown-induced tumor growth in mice." (PMID 30201002, 2018). "Furthermore, the knockdown of FBP1 alone promoted the tumor growth in mice, but the knockdown of c-Myc alone inhibited this growth." (PMID 30201002, 2018). "Next, we assessed the effect of the restored expression of FBP1 on tumor growth in mice." (PMID 28262837, 2017). "Our data and those from TCGA show that FBP1 is highly expressed in tumor-adjacent benign tissues." (PMID 28262837, 2017). "We found that increased expression of FBP1 significantly inhibited tumor growth in vivo." (PMID 28262837, 2017). "Increasing evidence suggests that FBP1 functions as a tumor suppressor." (PMID 28394358, 2017). "Although, DUOX1, GLS2 and FBP1 acts as liver tumor suppressor and mechanisms about tumor inhibiting of the three genes have been studied, the specific associations between prognosis of liver patients and expression of these three genes still remains unknown." (PMID 27079415, 2016). "According to the results of Fisher’s exact test and computational model (MLP and discriminant analysis), ultimately, Cox multivariate regression analysis was performed included the factors such as DUOX1, GLS2, FBP1, age, intrahepatic metastasis, tumor stage, histological grade and HBsAg." (PMID 27079415, 2016). "The repression of FBP1 reduced the volume and weight of the xenografts (NC versus siFBP1, P=0.0029) The tumors obtained from injection of CNE2-NC/SiFBP1-1# were performed to assess the tumor pathology by HE staining, FBP1 IHC staining and c-Myc IHC staining, and then analyzed by a pathologist." (PMID 26469968, 2015). "The interaction of menin with FBP1 could therefore contribute to the tumor suppressor function of menin or to the oncogenic function of menin depending on the targets that it is recruited to and the cell types that it is expressed in." (PMID 25132853, 2014).
tumor (continued). "FBP1 appears to be a functional tumor suppressor involved in the liver and colon carcinogenesis." (PMID 22039417, 2011). "First, the reversal of epigenetic silencing, potentially through the use of DNA methyltransferase inhibitors, could restore the expression of tumor suppressor metabolic hubs such as FBP1 and HPGD, thereby rebalancing cellular metabolism and limiting tumor progression." (PMID 40626022, 2025). "Interestingly previous studies already described a potential tumor suppressor role of FBP1 in BTC." (PMID 36900361, 2023). "In addition, lower tumor weights were observed in the FBP1 group than in the vector group." (PMID 36525508, 2023). "Indeed, it was found that NK cell function depends on stage tumour, thus, NK cells are functional during tumour initiation, mild dysfunctional during tumour promotion and irreversibly dysfunctional subsequently, being impossible to rescued them by FBP1 inhibition." (PMID 35406451, 2022). "Finally, overexpression of miR-24-1 suppressed tumor growth of RCC in an animal xenograft model, yet enhancer depletion led to loss of function of miR-24-1, suggesting that reactivation of FBP1 by miR-24-1 relies on enhancer integrity and can provide a potential treatment strategy for RCC." (PMID 35978816, 2022). "Similarly, higher FBP1 levels within our EAC cohort were connected to high amounts of CD3-positive T cell infiltration within the tumor a phenomenon for which survival benefit has already been described in this tumor entity." (PMID 35477823, 2022). "Thus, our findings define a new role of FBP1 in tumor suppression." (PMID 31938049, 2020). "Importantly, NF-κB appears to be crucial for the methylation of the FBP1 promoter in tumor cells." (PMID 32439898, 2020). "Therefore, we speculated that circFNDC3B-218aa exerted its tumor-suppressive effect in Snail/FBP1/EMT axis." (PMID 32241279, 2020). "Indeed, similarly to tumor-infiltrating T cells, NK cells in the mouse lung cancer are functional during tumor initiation, while assume a mild dysfunctional state during tumor promotion that can be reverted by pharmacological FBP1 inhibition." (PMID 32038612, 2019). "In this study, we hypothesized a novel role of FBP1 in the inhibition of tumor progression in PDAC." (PMID 30201002, 2018). "We also demonstrated that promoter hypermethylation-mediated silencing of FBP1 could be reversed by pharmacologic demethylation and restoration of FBP1 suppressed tumor cell growth through inducing G2-M phase cell cycle arrest and an increase in ROS generation." (PMID 22039417, 2011). "In addition to causing cell cycle arrest at the S phase, importantly in this study, the growth inhibitory effect of FBP1 as a tumor suppressor may also be mediated through enhancing the production of intracellular ROS." (PMID 22039417, 2011). "Firstly, our study was mainly based on in vitro experiments, and in the future, we will conduct a comprehensive investigation of the effects of FBP1 on the occurrence and development of GBM by establishing a mouse xenograft tumor model." (PMID 39902328, 2025). "Under hypoxic conditions, FBP1 overexpression suppresses the mRNA expression of the HIF-1α target genes PDK1, LDHA, GLUT1, and VEGF, inhibiting tumor growth, migration, and glycolysis in BLBC." (PMID 40100307, 2025). "The study aimed to elucidate the biological functions of FBP1 in GBM and to reveal its potential role in the tumor metabolism and immune microenvironment." (PMID 39902328, 2025). "The glucocorticoid Dexamethasone restores PCK1/FBP1 expression by activating the transcriptional coactivator PGC-1α, thereby reversing the Warburg effect and reducing tumor volume by 52% in animal models." (PMID 41293169, 2025). "In contrast to the function of FBP1 in inhibiting glycolysis, PKM2, a key enzyme in promoting glycolysis, was significantly upregulated in tumor tissues." (PMID 40100307, 2025).
tumor (continued). "Highly expressed FBP1 results in repressed glycolytic capacity, whereas inhibition of FBP1 with MB05032 sufficiently restores glycolysis and promotes tumor growth." (PMID 39806421, 2025). "EZH2-mediated promoter hypermethylation represses FBP1, while FBP1 itself inhibits PRC2 activity through direct interaction with EZH2—a tumor-suppressive feedback loop disrupted by genotoxic agents that stabilize EZH2." (PMID 40253354, 2025). "Whereas, to be tumor suppressors, ficolin 3 (FCN3), cytochrome P450 family 2 subfamily C member 8 (CYP2C8), and fructose-1,6-biphosphatase (FBP1) have been reported to be downregulated in HCC and inhibited the progression of HCC." (PMID 38664521, 2024). "Our analysis of critical BMAGs showed the tumour‐suppressive role of FBP1, highlighting its suppression in LUAD and its inhibitory effects on tumour proliferation, migration and invasion, in addition to its involvement in cell cycle and apoptosis regulation." (PMID 38693853, 2024). "Tumor cells usually show increased [18F]FDG uptake due to the overexpression of GLUT-1 transporter, increased intracellular hexokinase, and low FBP1." (PMID 36672305, 2023). "GPI1, TPI1, GAPDH, PGK1, and PKM2 were consistently upregulated in almost all tumor types, while PCK1, PCK2, and FBP1 were downregulated in tumors." (PMID 35246510, 2022). "The study found that circFNDC3B-218aa inhibited tumor progression and EMT by alleviating the inhibitory effect of Snail on FBP1 in colon cancer." (PMID 35936754, 2022). "Over-expression of CELF6 inhibits tumor cell proliferation, colony formation, cell migration and invasion by directly binding to the 3′UTR of FBP1 and stabilizing FBP1 transcripts." (PMID 35910766, 2022). "Therefore, FBP1 may inhibit the effect of glycolysis in tumor cells." (PMID 34363022, 2021). "Multiple genes, such as FBP1, PLOD2, VCAN, and CD44 have been demonstrated to participate in epithelial-mesenchymal transition (EMT) promotion of tumor metastasis." (PMID 33836688, 2021). "To observe subcutaneous tumor formation, we injected A2780 and SKOV3 cells either overexpressing FBP1 or harboring empty vector into the flanks of nude mice." (PMID 34363022, 2021). "Compared with normal kidney tissues, antibody stainings for ANKZF1, CD44, IDUA, KIF20A, PLOD2, and VCAN were high in ccRCC tumor tissues, whereas they were low for CHST6, HS6ST2, NDST3 and FBP1." (PMID 33836688, 2021). "Therefore, we speculated that circFNDC3B-218aa exerts a tumor-related role in Snail/FBP1/EMT axis." (PMID 32241279, 2020). "Meanwhile, RT-qPCR assays revealed that ALDH6A1, FBP1, HAO2 and PSAT1 were markedly under-expressed in tumor tissues in exceeding 60% cases, and that TYMP, HK3, P4HA3, IL4I1, CYP26A1 and CPT1B were over-expressed in tumor tissues in exceeding 70% cases." (PMID 32737333, 2020). "ENO3, FBP1, FBP2, GPD1, and ALDOB were all glycolytic pathway-related proteins with inhibitory effects on tumor." (PMID 33200655, 2020). "For example, glycolysis-associated enzymes such as phosphoenolpyruvate carboxykinase 1, 2 (PCK1, 2) and enzyme fructose-1,6-bisphosphatase 1 (FBP1), were downregulated in in two tumors, which resulted in glucose intake and kept tumor cells survive." (PMID 32127786, 2020). "In our study, we found that circFNDC3B-218aa suppressed tumor EMT progression was mainly dependent on inhibiting of Snail expression, subsequently enhancing FBP1-induced OXPHOS." (PMID 32241279, 2020). "Taken together, the results indicate that hypoxia supports the Warburg effect to promote tumor progression via GBE1 induction and that GBE1-mediated FBP1 suppression via FBP1 promoter methylation enhances HIF1α levels through NF-κB signaling in LUAD tissues." (PMID 32439898, 2020). "Fructose-bisphosphatase 1 (FBP1) palys negative regulation roles in glycolysis and affects some process of survival, proliferation and metastasis in tumor cells." (PMID 30867653, 2019).
tumor (continued). "Restored expression of FBP1 decreased glucose reduction and lactate secretion and inhibited HCC cell growth in vitro and tumor growth in mice." (PMID 28262837, 2017). "Knockdown of FBP1 resulted in an increase in Ki-67 staining compared with the control group, but knockdown of TRIM28 decreased Ki-67 staining in tumor tissues compared with control tumors." (PMID 28394358, 2017). "In order to determine the model robustness for predicting prognosis of HCC patient after tumor resection, we finally resorted to ROC curve analyses by individually using the expression of each marker (DUOX1, GLS2, FBP1)." (PMID 27079415, 2016). "With this immunohistochemical procedure, we found different patterns between FBP1, FBP3 and c-myc expression in the different tumor types." (PMID 19087307, 2008). "Conversely, downregulation of FBP1 and HPGD, coupled with their hypermethylation, reinforces the metabolic shift toward glycolysis and potentiates prostaglandin-driven inflammation, both of which are key drivers of tumor progression." (PMID 40626022, 2025). "Other preclinical evidence suggests that FBP1 overexpression acts as a tumor suppressor; however, the lack of tumorigenesis with salicylate suggests that allosteric inhibition is a way of inhibiting FBP1, without promoting tumor progression." (PMID 40400417, 2025). "In contrast, the downstream gluconeogenesis enzyme fructose-1,6-bisphosphatase 1 (FBP1) suppresses glycolysis and tumor growth through non-enzymatic processes." (PMID 36837801, 2023). "Interestingly, some metabolic enzymes, such as fructose-bisphosphatase 1 (FBP1), pyruvate kinase M2 (PKM2) and malate dehydrogenase 1 (MDH1), act as a tumor suppressor or oncogenic factor alongside their canonical role." (PMID 36419156, 2022). "It was reported that the expression of gluconeogenic enzymes PCK1, PCK2, and FBP1 predominantly decreased in HCC, and their forced expression induced apoptosis under glucose deprivation conditions, demonstrating the anti-tumor effects of gluconeogenesis in HCC." (PMID 36092708, 2022). "FBP1 is a gluconeogenesis enzyme, and inhibits glycolysis and tumor growth, partly by non-enzymatic mechanisms." (PMID 36430241, 2022). "The use of FBP1 inhibitor drifts back the dysfunctional phenotype of NK cells during tumor promotion but not during tumor progression." (PMID 36032082, 2022). "In addition, FBP1 plays a role in inhibiting the cell cycle and EMT pathways, and thus, FBP1 had an inhibitory effect on tumor growth, invasion, and metastasis." (PMID 33564363, 2021). "Simultaneously, NK cell metabolism is markedly altered within the tumor-microenvironment, as many molecules, such as FBP1, can directly impair tumor-infiltrated NK cell viability, independent of glycolysis." (PMID 34177887, 2021). "We found that 47.2% (n = 177) of the tumor tissues exhibited high-FBP1 immunostaining (defined as moderate or strong), and 52.8% (n = 198) exhibited low-FBP1 immunostaining (defined as negative or weak)." (PMID 34363022, 2021). "Moreover, we found that circFNDC3B-218aa inhibited tumor progression and epithelial-mesenchymal transition (EMT) via alleviating the repressive effect of Snail on FBP1 in colon cancer." (PMID 32241279, 2020). "Rationale: Fructose-1, 6-bisphosphatase 1 (FBP1), a rate-limiting enzyme in gluconeogenesis, was recently shown to be a tumor suppressor and could mediate the activities of multiple transcriptional factors via its non-canonical functions." (PMID 32754266, 2020). "The authors showed that pharmacological inhibition of FBP1 can revert the dysfunctional phenotype of NK cells during tumor promotion, but not during tumor progression." (PMID 32038612, 2019). "Interestingly, insulin signaling, including the FBP-1 gene, was the most highly enriched in down-regulated DEGs, but we know that down-regulation of FBP1 promotes tumor metastasis and indicates poor prognosis in other cancers." (PMID 30205506, 2018).
tumor (continued). "However, double knockdown of FBP1 and TRIM28 abolished TRIM28 knockdown-induced inhibition of SK-Hep-1 tumor growth in mice." (PMID 28394358, 2017). "These non-enzymatic functions of FBP1 implicate the metabolic regulation of hypoxic responses in tumor formation." (PMID 28580187, 2017). "The total metabolic tumor volume (MTV) is a direct consequence of the alterations in the expression levels of glucose transporter 1 (GLUT-1), fructose bisphosphate aldolase A (ALDOA), and fructose bisphosphatase 1 (FBP1)." (PMID 28335509, 2017). "Additionally, we demonstrate that restoration of FBP1 expression in HCC cells blocks glycolysis and inhibits tumor growth." (PMID 28262837, 2017). "Restoration of FBP1 expression in human HCC cell lines significantly inhibited cell growth, suggesting that it might function as a tumor suppressor." (PMID 24633177, 2014). "FBP1 and FBP3 were shown to be co-expressed in most tumor entities." (PMID 19087307, 2008). "Although the FBP1 and FBP3 genes are located on different chromosomes in humans (1p31.1 and 9q34.11, respectively) they show a strikingly parallel expression pattern through different tumor entities and tumor samples within an entity." (PMID 19087307, 2008). "A mechanistic exploration revealed that FBP1 increases FBXW7 protein levels by inhibiting the auto-ubiquitination of FBXW7, which promotes mTOR ubiquitination to inhibit mTOR levels, thereby inhibiting glycolysis and enhancing the anti-tumor effects of radiation." (PMID 40100307, 2025). "While FBP1 is mediated by transforming growth factor beta (TGF-β) in the tumour microenvironment, CAFs are the origin of TGF-β, and CAFs are the most abundant cells in the tumour stroma that are recruited by platelet-derived growth factor secreted through the tumour." (PMID 37108242, 2023). "To date, the role of FBP1 in anti-tumor immune response is not well-understood." (PMID 36358906, 2022). "Interestingly, the shifts in Treg and anti-tumor T cell expression were accompanied by increased expression of the exhaustion markers PD-L1 (3.83-fold, p=0.011), TIGIT (3.61-fold, p=0.011), and tumor suppressor FBP1 (9.23-fold, p=0.013) in women." (PMID 36387163, 2022). "Drugs that solely activate FBP1's enzymatic activity may not be sufficient to fully trigger its tumor suppressive function." (PMID 29991493, 2018). "Besides glucose metabolism, we also demonstrated that FBP1 could inhibit HCC cell proliferation and tumor growth in mice." (PMID 28262837, 2017). "Thus, as both FBP1 and CPT1A are inhibitive of tumor growth and cell survival under stress, both genes display tumor suppressor phenotypes; though whether lipid deposition is a common mechanism of the effect remains to be investigated." (PMID 29176561, 2017). "In addition, promoter methylation was frequently detected by using MSP in tumor samples but not non-tumor tissues, indicating that downregulation of FBP1 was involved in the carcinogenesis of human liver and other digestive cancers." (PMID 22039417, 2011). "Once FBP1 promoter methylation was detected at a high frequency in primary carcinoma tissues but not non-tumor normal gastric tissues, FBP1 promoter methylation may be a potential biomarker for cancer diagnosis." (PMID 22039417, 2011). "Unfortunately, for lack of large numbers of tumor tissues, we couldn't test FBP1 methylation in abundant tissues and further analyze its association with clinical characteristics, such as age, gender, tumor grade and survival rate." (PMID 22039417, 2011). "In addition to inhibiting tumor growth by antagonizing glycolysis, FBP1 inhibits cell proliferation through a series of non-glycolytic pathways; for instance, by acting as a transcriptional regulator of DNA transcription, or directly binding to mRNA to regulate mRNA translation and stability." (PMID 40100307, 2025). "We discovered that FBP1-S271A expression, but not FBP1-WT inhibited PTEN knockdown-enhanced tumor growth in vivo." (PMID 36237339, 2022).